TP63 (tumor protein p63)
Diseases named in the same sentence as TP63 in open-access papers (continued):
Sharing a sentence is not in itself a finding about the gene and the disease.
tumor (continued). "Moreover, up to 80% of OSCC patients show overexpression and/or genomic amplification of TP63, and these events are associated with poor tumour differentiation and patient prognosis." (PMID 34680271, 2021). "Furthermore, recent studies suggest that basal-like and classical molecular subtypes coexist in the same tumour with epigenetically driven TP63 based reprogramming causing squamous transdifferentiation associated with tumour aggressiveness, including increased invasiveness and tumour size." (PMID 34711883, 2021). "Cas9-mediated ΔNp63 inactivation completely arrested tumor growth in mice transplanted with BxPC3-Cas9 cells transduced with TP63 sgRNAs, suggesting that PDA tumors rely on p63 for tumor growth in vivo." (PMID 39791744, 2025). "Transcription factors (TFs) associated with tumor metastasis and progression, such as SOX9, HMGA2, TP63, NFIL3, and IRF6, exhibited high transcriptional activity in the ITGA2hi‐PTC subcluster." (PMID 40985182, 2025). "We identified tumor-specific super-enhancer domains (T-SEDs) enriched for key TFs, including TP63, FOSL1, and JUND, and demonstrated that these domains regulate genes critical to oncogenic signaling and proliferation." (PMID 41323280, 2025). "To investigate the tumor-suppressive mechanisms of decursin, we performed Western blot analysis of ESCC-associated oncoproteins TP63 and SOX-2." (PMID 40508204, 2025). "Tumor growth was monitored every 3 days, and we observed slower tumor progression in the shTP63 group compared to the ctrl group, suggesting that TP63 knockdown sensitized tumors to RSL3 treatment." (PMID 40796737, 2025). "In conclusion, we established an ALK-negative ALCL PDX and cell line model harbouring TP63 rearrangement that can not only recapitulate the original characteristics of the patient tumour, but also propagate in vivo." (PMID 40715645, 2025). "The results showed that compared to the control group, tumor cells exhibited increased lipid peroxidation and ROS levels after TP63 was silenced, indicating that TP63 silencing promoted ferroptosis in tumor cells." (PMID 40796737, 2025). "We mapped H3K27ac-marked super-enhancers (SEs) via ChIP-seq in HPV+ patient-derived xenografts (PDXs) and normal oropharyngeal mucosa, identifying tumor-specific SE domains (T-SEDs) enriched for transcription factors (TFs) including TP63, FOSL1, and JUND." (PMID 41323280, 2025). "We established a patient-derived xenograft (PDX) and in vitro model (designated PTCL-S1) of TP63-rearranged ALK-negative ALCL from the primary tumour site of a 55-year old Chinese woman." (PMID 40715645, 2025). "Significantly upregulated eRNAs were identified near key oncogenes, including CLDN1, TP63, and EGFR, confirming transcriptional activation at these tumor-associated SEs." (PMID 41323280, 2025). "To evaluate the functional role of ΔNp63 in vivo, we generated U251 and U118 tumor cell lines with stable TP63 knockdown (shTP63) or a control vector (ctrl) and established subcutaneous tumor formation mouse models." (PMID 40796737, 2025).
tumor (continued). "TP63, functioning as a central regulator of squamous epithelial differentiation, promotes tumor progression through dual mechanisms—activating proliferative pathways (NOTCH and Wnt/β-catenin signaling) while inhibiting apoptosis mediators like BAX and PUMA." (PMID 40508204, 2025). "Conversely, the downregulation of NFS1, GCLC, TP63, CD44, and SRC suggests a potential attenuation of antioxidant defense systems, thereby predisposing tumor cells to lipid peroxidation-mediated cell death." (PMID 40868287, 2025). "A higher proportion of CD8+ T cells was observed in TP63-low tumor samples (median = 52.29%) than TP63-high tumors (median = 40.07%)." (PMID 38509096, 2024). "Here we reveal a tumor-extrinsic role of TP63 in promoting immune evasion of SCC cells by suppressing the IFNγ-STAT1 signaling." (PMID 38509096, 2024). "By integrating the mechanistism score with tumor stage, we developed a clinical scoring model based on TP63 and SLC7A5, employing nomograms for the prediction of one-year, three-year, and five-year survival rates in patients." (PMID 39234254, 2024). "NUT‐fusion proteins drive the formation of hyperacetylated chromatin “megadomains” or “superenhancers,” including the enhancer regions of genes such as MYC and TP63, which inevitably promote tumor growth and prevent differentiation." (PMID 40336973, 2024). "The tissue sections were all judged by professional pathologists, and the parts stained with TP63 antibody were all tumor cells." (PMID 38791062, 2024). "In the tumour cells that reside post treatment, 40 candidates were found to have increased expression alongside enriched accessible binding motifs, including TP63, TCF4 and the well-defined regulator of OC cancer stem-cell differentiation, TWIST131." (PMID 39341888, 2024). "Together, our findings elucidate a tumor-extrinsic function of TP63 in promoting immune evasion of SCC cells." (PMID 38509096, 2024). "Second, both genes associated with T-cell activation and response, like LCK, and genes involved in other aspects of tissue organization and tumor biology, like TP63, have roles in immunotherapy response." (PMID 38793063, 2024). "Silencing of TP63 enhances the anti-tumor efficacy of PD-1 blockade by promoting CD8+ T cell infiltration and functionality." (PMID 38509096, 2024). "Previous studies indicated that TP63α mRNA forms (TAP63α and ΔNP63α) predominate in normal tissues and tumours, and other isoforms represent only a fraction of the overall TP63 mRNA." (PMID 39404067, 2024). "Our previous studies have established TP63 as an SCC-specific master regulator TF27,28,32, and the specific expression profile of TP63 in SCCs was validated at the pan-cancer level using RNA-seq data of human tumor samples from The Cancer Genome Atlas (TCGA)." (PMID 38509096, 2024). "This subpopulation suppresses ferroptosis in malignant cells through the transcriptional upregulation of SLC7A5 mediated by high TP63 expression, thereby promoting tumor growth and resistance to immunotherapy." (PMID 39234254, 2024). "We found a notable enrichment of FST within TP63-expressing tumor epithelial cells driven by the activation of the MAPK signaling pathway." (PMID 38392348, 2024). "To determine the relationship between tumor-intrinsic TP63 expression and T cell infiltration, we first stratified these 60 patient samples as either TP63-high or -low groups (top/bottom 15%) based on the expression level of TP63 in 97,631 tumor cells." (PMID 38509096, 2024). "Tumor protein p63 (TP63) has two isoforms, in which TAp63 is thought of as a tumor suppressor, while ΔNp63 is considered as an oncogene." (PMID 38678251, 2024).
tumor (continued). "In comparison with the Scramble group, TP63-knockdown strongly augmented tumor cell killing by CD8+ T cells in both MOC22 and AKR cell lines, at different effector: target ratios." (PMID 38509096, 2024). "Further investigations on potential regulation on macrophages and neutrophils by TP63 are thus necessary to further understand the complexity of tumor microenvironment and immune response of SCCs." (PMID 38509096, 2024). "Previous research also found that TP63 cooperated with other transcription factors such as NF-κB to influence the tumor microenvironment (TME)." (PMID 38791062, 2024). "We demonstrate that the expression of TP63 is significantly correlated with early tumor recurrence in ESCC." (PMID 38791062, 2024). "Silencing TP63 has been shown to enhance the anti-tumor efficacy of PD-1 blockade by promoting the infiltration and functionality of CD8+ T cells." (PMID 38785789, 2024). "RB1, PRDM1, and TP63 expression was significantly downregulated in tumor samples with distant metastasis compared to tumor samples without metastasis, based on both TCGA and GSE30219 datasets." (PMID 38057344, 2023). "In vitro studies have shown that NUT fusion proteins drive tumor growth and block differentiation through aberrant histone acetylation depending on the targeting of Myc and TP63 genes by BRD bromodomains." (PMID 36936659, 2023). "Statistical analysis further demonstrated a significant decrease in TP63 expression in the tumor group compared to the normal group." (PMID 38152394, 2023). "TP63 plays an important role allowing cells to undergo apoptosis in response to DNA damage and is involved in tumor and metastasis suppression." (PMID 37228816, 2023). "Conversely, ELN, EFEMP1, and UCHL1 were expressed at low levels, whereas TP63 was expressed at high levels in tumor tissues in contrast with ANT." (PMID 37441420, 2023). "We reanalyzed one bulk RNA-seq and one scRNA-seq datasets of hESCC samples that we reported previously and found that TP63 RNA levels in tumor samples were significantly higher than that in normal tissue samples." (PMID 38097539, 2023). "Treatment with siRNAs targeting TP63 (siTP63) or ATP1B3 (siATP1B3) significantly suppressed tumor-promoting functions of HNSCC cells, including cell viability, tumor sphere formation, migration, and invasion." (PMID 36828832, 2023). "ELN, EFEMP1, and UCHL1 were expressed at low levels whereas TP63 was expressed at high levels in tumor tissues in contrast with ANT." (PMID 37441420, 2023). "We found that TP63 is also significantly overexpressed in primary tumor samples compared to normal tissues in TCGA LUSC data compared to other cancer types, ranking high among transcription factors expressed in this cancer subtype." (PMID 37150829, 2023). "For patients P10 and P11, the staining results also showed the presence of NKX2-1 and TP63 double-positive cells in tumor tissues." (PMID 35962452, 2022). "The ΔNTP63 isoforms are characterized by transcription initiation at exon 4 and account for more than 99% of total TP63 in both normal and tumor samples." (PMID 36970727, 2022). "At the same time, there were significant differences in the expression of these genes in tumor samples and normal samples, with the exception of TP63, KLHL24, and LAMP2, which were all downregulated in tumors." (PMID 36147441, 2022).
tumor (continued). "In the 27 PRGs, apart from CASP4, CHMP6, CHMP7, GSDMD, and TP63, the other 22 PRGs were expressed differentially at a significant level between primary tumor and paracancerous samples." (PMID 35938142, 2022). "The 12 downregulated genes were functionally involved in 8 pathways, including tumor maker (TP63, MMP9, and EGR3 genes) and antigen processing (HLA-F-AS1 and HLA-A genes)." (PMID 35915657, 2022). "Both these tumor suppressors are known to be mutated in HNSCC and loss of expression of the same has been linked to cancer progression while TP63 is known to promote survival in HNSCC patients." (PMID 34796107, 2021). "Tumor samples from each SCC cohort were stratified as either TP63-high (top 30%) or TP63-low (bottom 30%) based on expression of this TF." (PMID 34272396, 2021). "Increasing evidence demonstrates that TP63 proteins are tumor suppressors which block the metastatic potential of tumor cells, although an oncogenic TP63 isoform has also been identified." (PMID 33216733, 2020). "We previously found that Syntaxin Binding Protein 4 (STXBP4) plays a crucial role in lesion growth and, therefore, clinical outcomes in LSCC patients through regulation of tumor protein p63 (TP63) ubiquitination." (PMID 32993587, 2020). "Of note, the mammary epithelium-like structure with differentiation markers (both EPCAM and TP63) was observed in the xenografts generated by tumor sphere cells." (PMID 31196164, 2019). "Although evidence suggests that TP63 functions as a tumor suppressor, TP63 is overexpressed in many cancers, including head and neck cancers." (PMID 29988031, 2018). "Consistently, immunofluorescence of ACP histological sections revealed the expression of BCL11B and TP63 exclusively in tumour cell compartments, including clusters, palisading epithelium and stellate reticulum, but not within surrounding reactive tissue." (PMID 29541918, 2018). "Our data suggest that TP63 (predominantly ΔNp63) likely plays a critical role in oral tumorigenesis and tumor progression." (PMID 28423539, 2017). "TP63 and TP73 are overexpressed in human cancers, and their loss affects tumor progression and metastasis." (PMID 28258440, 2017). "The amplification of PIK3CA, PTEN, KRAS, SOX2, DVL3, and TP63 were present in all tumor samples in M7 and M9, including N4 in M7." (PMID 29050228, 2017). "PD-L1 was expressed in tumor cells of 26.3% patients, and TP63 was immunostained in nucleoli of tumor cells of 31.6% cases." (PMID 28403071, 2017).
tumor (continued). "31.6% patients showed TP63 immunoreactivity in the nucleoli of tumor cells with 1.3% case of weak positive, 13.1% of moderate, and 17.2% of strong positive." (PMID 28403071, 2017). "Intriguingly, the expression levels of TP63 and ΔNp63 were significantly higher in the tumor buddings (and the ITFs) than in their superficial or central counterparts." (PMID 28423539, 2017). "There was the expected corresponding decrease in basal cell markers (KRT5 and TP63) and increase in expression of luminal cytokeratin markers in tumor cells (KRT8 and KRT18)." (PMID 27935821, 2017). "DLBCL with PD-L1 or TP63 expression in tumor cells showed low International Prognostic Index (IPI) score (P = 0.007, P = 0.009)." (PMID 28403071, 2017). "An in vivo model of SQCC (not of lung origin) showed that TP63 signaling is essential for tumor growth, and identified a survival program governed by TP63 that involves signaling from FGFR2 activated by stroma-derived ligand." (PMID 24722523, 2014). "We confirmed TP63 as having dominant expression of the short DeltaNp63 isoform in HNSCC tumor samples, consistent with prior reports." (PMID 24675808, 2014). "In our exon array analysis, manual review of TP63 gene plots predicted 25 of 44 tumor samples with a splicing pattern predominantly expressing the shorter DeltaNp63 isoforms." (PMID 24675808, 2014). "Our results show that SOX2 and TP63 proteins are found in the nucleus of most tumour cells in HR-HPV+ve SCCC biopsies." (PMID 25531390, 2014). "Notably, these genes contained major BL-specific driver genes, such as CD9, MYC, TP63, and cJUN, indicating a direct tumor cell-intrinsic repression of BL features." (PMID 39762215, 2025). "Through transcriptomic profiling and protein–protein interaction (PPI) network analysis, we identified a subset of ferroptosis-related genes such as MAPK1, HMOX1, and TP63 that exhibit potential involvement in tumor progression, oxidative stress regulation, and immune interaction." (PMID 40868287, 2025). "As increased copy number aberrations often correlate with increased activity of the amplified gene, we posited that the amplification of EGFR and TP63 in HNSCC may explain the upregulation of FST within tumor epithelial cells." (PMID 38392348, 2024). "Given the prominent and essential role of IFNγ signaling in anti-tumor immunity, we hypothesized that over-expression of TP63 facilitates immune evasion of SCC cells by suppressing the IFNγ signaling pathway." (PMID 38509096, 2024). "Moreover, our data from mouse models and human patient samples demonstrate that high expression of TP63 impedes CD8+ T cell infiltration and tumor killing; inhibition of TP63 enhances the efficacy of PD-1 mAb therapy." (PMID 38509096, 2024). "The discovery of the relationship between tumor recurrence and TP63 not only provides us with more information, but through further research into its correlations, it may help identify additional mechanisms contributing to tumor recurrence." (PMID 38791062, 2024).